ISG15 (ISG15 ubiquitin like modifier)
Diseases named in the same sentence as ISG15 in open-access papers (continued):
Sharing a sentence is not in itself a finding about the gene and the disease.
head and neck cancer (2 papers, 2023 to 2024). A primary or metastatic malignant neoplasm affecting the head and neck. "ISG15 has been recognized by multiple previous studies as one of the highly upregulated genes and a potential biomarker in head and neck cancer, yet its involvement in HNSCC tumorigenesis is barely understood." (PMID 38926796, 2024). "Interestingly, ISG15 has been recognized by multiple previous studies as one of the highly upregulated genes and potential biomarkers in head and neck cancer, but how it is involved in HNSCC tumorigenesis is largely unclear." (PMID 38926796, 2024). "Induction of IFNβ post-IR followed by the interplay of IFN-induced proteins (STAT1, ISG15) and cytokines (IL-1β, IL-6, MIF) hints towards IR-induced inflammation contributing to initiation and progression of oral mucositis that affects a majority of head and neck cancer patients." (PMID 37384298, 2023).
head and neck squamous cell carcinoma (2 papers, 2025). A squamous cell carcinoma that arises from any of the following anatomic sites: lip and oral cavity, nasal cavity, paranasal sinuses, pharynx, larynx, and salivary glands. "Additionally, ISG15 released by necroptotic head and neck squamous cell carcinoma (HNSCC) cells can reprogram the microenvironment to enhance tumor progression and metastasis." (PMID 40719862, 2025).
idiopathic pulmonary fibrosis (2 papers, 2023 to 2026). Idiopathic pulmonary fibrosis (IPF) is a nonneoplastic pulmonary disease that is characterized by the formation of scar tissue within the lungs in the absence of any known cause. "Transcriptomic data of people living with HTLV-1, HAM/TSP patients and idiopathic pulmonary fibrosis patients confirm in vivo expression of the in vitro gene signature, whereas single cell RNA-seq identified a unique myeloid subset in human lung, characterized by co-expression of CCL2/ISG15/CXCL10." (PMID 42026465, 2026).
inflammatory bowel disease (2 papers, 2022 to 2023). A spectrum of small and large bowel inflammatory diseases of unknown etiology. "Elevated CXCL1 expression in the gut of patients with inflammatory bowel disease may also depend on other factors such as interferon-stimulated gene product 15 (ISG15)/ubiquitin cross-reactive protein (UCRP), IL-36α and IL-36γ, and the influence of gut microbiota." (PMID 35806156, 2022).
invasive breast carcinoma (2 papers, 2008 to 2021). A carcinoma that infiltrates the breast parenchyma. "In invasive breast carcinomas (ductal type) ISG15 expression was generally more abundant than in either ductal carcinoma in situ or normal breast tissue." (PMID 18627608, 2008). "Using semiquantitative real-time PCR, cDNA dot-blot hybridisation and immunohistochemistry, we systematically analysed ISG15 expression in invasive breast carcinomas (n = 910) and normal breast tissues (n = 135)." (PMID 18627608, 2008).
kidney injury (2 papers, 2023 to 2024). Trauma to the kidney. "In summary, we reported that increased ISG15 and TGFβR1 expression in the models of IRI-, cisplatin- or UUO-induced kidney injury, and improved kidney function was found in Isg15 KO mice." (PMID 39113797, 2024). "Expression of ISGs (Mx1, Isg15, Isg20, Ifitm1, Bst2, and Oas1), and immune cell markers Lyz2 and Cd68 were markedly lower in 3TC mice with FA-induced kidney injury compared to controls." (PMID 36732547, 2023). "Moreover, knockout of TGFβR1 blocked ISG15's fibrosis-exacerbating effect in HK-2 cells, while overexpression of TGFβR1 abolished the renal protective effect of ISG15 knockout during IRI-induced kidney injury." (PMID 39113797, 2024).
lung disease (2 papers, 2024). "Additionally, single-cell RNA sequencing of lung tissue highlighted several immune cell types that may be involved in the pathophysiology of MDA5+ DM lung disease, including ISG15+ CD4+ T cells, ISG15+ CD8+ T cells, and proliferating CD8+ T cells." (PMID 39588376, 2024).
lupus nephritis (2 papers, 2023 to 2025). Glomerulonephritis in the context of systemic lupus erythematosus. "Moreover, we could detect cluster 12 as ISGhigh B cells which had upregulated expression of ISG15, similar to the findings in lupus nephritis." (PMID 38129902, 2023).
Mendelian susceptibility to mycobacterial diseases (2 papers, 2020 to 2023). "In humans, biallelic mutations in ISG15 were reported to result in an impaired IFN-γ mediated immunity, leading to an increase predisposition to mycobacterial infections in most cases, as also observed in patients with Mendelian Susceptibility to Mycobacterial Diseases (MSMD)." (PMID 32944031, 2020).
neuroblastoma (2 papers, 2019 to 2024). Neuroblastoma (NB) is the most common solid, extracranial childhood tumor. "A previous study has suggested that the mRNA expression of ISG15 and ISG43 negatively regulated by RNase L in an RNase L-deficient murine neuroblastoma cell line." (PMID 30941371, 2019).
non-small cell lung carcinoma (2 papers, 2021 to 2024). A group of at least three distinct histological types of lung cancer, including non-small cell squamous cell carcinoma, adenocarcinoma, and large cell carcinoma. "Interestingly, the protein expression level of ISG15 showed a subtle yet significant positive correlation with the protein expression level of SIRT1 in the complete set of cancer types (R = 0.15, P = 0.0042) as well as in non-small cell lung carcinoma (NSCLC) (R = 0.26, P = 0.0441)." (PMID 38443596, 2024).
Osteopenia (2 papers, 2013 to 2020). Osteopenia is a term to define bone density that is not normal but also not as low as osteoporosis. "Consistently, ISG15 null mice have moderate osteopenia consistent with overall increased osteoclastogenesis and bone resorption, suggesting that this could be a universal regulatory mechanism." (PMID 32202502, 2020).
osteopetrosis (2 papers, 2019 to 2021). Osteopetrosis, also known as marble bone disease, is a descriptive term that refers to a group of rare, heritable disorders of the skeleton characterized by increased bone density on radiographs. "Interestingly, the upregulated protein ISG15 (2.305 fold change, P = 0.00046) was involved in bone formation and highly enriched in the RIG-I-like receptor signaling pathway, which may have a close relationship with the disease of osteopetrosis." (PMID 31412925, 2019).
Parkinson disease (2 papers, 2022). A progressive degenerative disorder of the central nervous system characterized by loss of dopamine producing neurons in the substantia nigra and the presence of Lewy bodies in the substantia nigra and locus coeruleus. "However, if ISG15 is elevated in Parkinson’s patients has not been studied." (PMID 35159348, 2022).
preeclampsia (2 papers, 2022 to 2025). Preeclampsia is a hypertensive disorder of pregnancy that is characterized by new-onset hypertension with proteinuria presenting after 20 weeks of gestation, and depending on mild or severe forms may initially present with severe headache, visual disturbances, and hyperreflexia. "Pertinently, reduction in levels of ISG15 that is required for ISGylation is associated with preeclampsia and knockdown of ISG15 expression impairs invasion of HTR8/SVneo cells in culture." (PMID 40221000, 2025). "In addition, since we didn’t observe a difference in maternal serum ISG15 levels, downregulation of ISG15 levels in the maternal-fetal interface in preeclampsia can be linked to a local dysregulation rather than a systemic impact." (PMID 35837332, 2022).
primary Sjogren’s syndrome (2 papers, 2021 to 2024). "Raised criterion of ISG15 has been observed in the saliva and serum of sufferers with major Sjogren’s syndrome, and ISG15 expression is also relatively high in SLE sufferers, correlating with disease progression prior to treatment." (PMID 39872521, 2024). "Finally, we examined this IRG signature (ISG15, SIGLEC1, STAT1 RSAD2, IFI27 and IFI44L) in peripheral blood mononuclear cells (PBMCs) collected from a smaller cohort of healthy controls, disease controls, AAV and primary Sjogren’s syndrome (pSS) patients." (PMID 33859290, 2021).
proteinopathy (2 papers, 2011 to 2022). "Increased expression of ubiquitin pathway antagonist ISG15 has been identified as a probable cause of defective mitophagy and proteinopathy-induced neuronal death in neurodegenerative diseases." (PMID 35958988, 2022). "Development of small molecule inhibitors targeting ISG15 pathway could prevent proteinopathy associated with A-T and, consequently, neurodegeneration." (PMID 21298066, 2011).
renal fibrosis (2 papers, 2024 to 2025). A final common manifestation of a wide variety of chronic kidney diseases characterized by glomerulosclerosis and tubulointerstitial fibrosis. "Together, our results reveal a novel role of ISG15 in regulating renal fibrosis and suggest a potential therapeutic approach against AKI and following AKI-to-CKD transition." (PMID 39113797, 2024). "Although it is challenging to explain the effects of ISG15 in these kidney injuries using a single mechanism, our data nevertheless indicate that ISG15 modulates renal fibrosis, a common pathway influencing kidney injury in these models." (PMID 39113797, 2024). "However, the knockout of ISG15 led to a marked reduction in collagen deposition, effectively mitigating renal fibrosis." (PMID 40462493, 2025). "And, knockout of ISG15 led to decreased TGFβR1 and its downstream p-Smad2 levels, reduces transcription levels of fibrotic genes such as α-SMA, Fn1, and Vimentin, ultimately inhibited renal fibrosis." (PMID 39113797, 2024).
skin ulceration (2 papers, 2022 to 2023). "In this report, we describe novel variants found in two different families that result in complete ISG15 deficiency and severe skin ulceration." (PMID 38115997, 2023). "We have investigated two siblings with unexplained recurring skin ulcerations that healed with scar formation under corticosteroid treatment and, unexpectedly, identified a homozygous nonsense mutation of ISG15 as the most plausible etiology in both cases." (PMID 34847081, 2022). "Together, these findings suggested that dysregulation of collagen homeostasis and expression of adhesion molecules might act in concert with oxidative stress and hyperinflammation in the pathogenesis of skin ulcerations in ISG15 deficiency." (PMID 34847081, 2022). "Considering the results of the 3D model and the cell migration studies together, it appears that a combined therapy with RUX/DOXY/TGF-β1 is a potential treatment for skin ulcerations in ISG15 deficiency, but that the effects of TGF-β1 on cell migration require clarification." (PMID 34847081, 2022).
steatosis (2 papers, 2022 to 2025). Increased lipid within the cytoplasm of cells. "An increase in ISG15 was found in pathological sections from HCC tissues with steatosis compared with those from steatosis‐free HCC." (PMID 40126377, 2025). "Here, we explored the roles of the ISG15 system in β-catenin activation and in the pathogenesis of alcohol-induced liver injury and steatosis." (PMID 36259544, 2022).
viral myocarditis (2 papers, 2023 to 2024). Myocarditis that is caused by an infection with a viral agent. "ISG15 limits the cellular damage caused by viral myocarditis; whereas our group recently reported induction and a pathogenetic role of ISG15 in the adverse ventricular remodeling that occurs in response to pressure overload." (PMID 38665231, 2024). "Secondly, at first glance the findings herein reported may appear to be at variance with those observed in the setting of viral myocarditis where ISG15 induction was reported to preserve cardiomyocyte health." (PMID 37115698, 2023).
acute myeloid leukemia (1 paper, 2025). Acute myeloid leukemia (AML) is a group of neoplasms arising from precursor cells committed to the myeloid cell-line differentiation. "Additionally, studies have demonstrated reduced expression of UBE2L6 in primary acute myeloid leukemia (AML) cells, where silencing UBE2L6 inhibits ATRA-induced ISG15 conjugation, thus impairing isgylation and hindering AML cell differentiation." (PMID 40990020, 2025).
adenoma (1 paper, 2024). A neoplasm arising from the epithelium. "Top over-represented EV proteins from the adenoma ZMTH3 were mainly related to immune response (ISG15, BST2, IFI44), while top under-represented proteins identified in the adenoma ZMTH3 EVs were associated with migratory and adhesion activity (MXRA8, TNN, SERPINB8), similar to the WCLs." (PMID 39462388, 2024).
adenovirus infection (1 paper, 2023). "Of these, SOCS3, OASL, ISG15, and IFIT1 were found to be involved in the process of adenovirus infection and were thus regarded as candidate genes." (PMID 37017816, 2023). "Transcriptome sequencing showed that the expression levels of SOCS3, OASL, ISG15, and IFIT1 increased significantly over time, especially at 48 hpi (except SOCS3) and 72 hpi, suggesting that these genes might play an important role in adenovirus infection." (PMID 37017816, 2023).
anemia (1 paper, 2011). A reduction in the number of red blood cells, the amount of hemoglobin, and/or the volume of packed red blood cells. "However, this faster response did not lead to accelerated recovery from anemia in ISG15-/- mice (data not shown), a phenotype reminiscent to that described in STAT1-deficient mice." (PMID 22022510, 2011).
antisynthetase syndrome (1 paper, 2025). Antisynthetase (AS) syndrome is a clinically heterogeneous form of idiopathic inflammatory myopathy characterized by myositis, arthralgia, Raynaud phenomenon, mechanic hands, interstitial lung disease (ILD), and serum autoantibodies to aminoacyl transfer RNA synthetases (anti-ARS). "Type I IFN-inducible genes, such as ISG15 and MX1, were elevated at intermediate levels, lower than those seen in DM but similar to antisynthetase syndrome." (PMID 40568658, 2025).
brain injury (1 paper, 2022). Acute and chronic (see also brain INJURIES, CHRONIC) injuries to the brain, including the cerebral hemispheres, CEREBELLUM, and brain STEM. "In patients with ALS, elevated levels of ISG15 and ISGylation in the CSF were significantly higher in post-traumatic brain injury ALS compared with those in non-traumatic brain injury ALS." (PMID 36325336, 2022).
cardiomyopathy (1 paper, 2021). A disease of the heart muscle or myocardium proper. "As a third ISG15-sensitive virus we tested CVB3, a Picornavirus that can lead to cardiomyopathy and that is known to be ISG15 sensitive." (PMID 34599178, 2021).
chlamydial infection (1 paper, 2025). "In conclusion, our data demonstrate that FGT epithelial cells locally secrete ISG15 in response to Ct infection and that this secreted ISG15 plays distinct roles during chlamydial infection of the genital tract." (PMID 40627782, 2025). "The data thus far indicate that ISG15−/− mice exhibit reduced efficiency in clearing chlamydial infection." (PMID 40627782, 2025). "Evidence of uterine horn pathology and reduced IL-10 levels in the FGT of infected ISG15−/− mice further supports a critical dual function of ISG15 in controlling chlamydial infection and modulating the resulting inflammatory responses." (PMID 40627782, 2025). "We hypothesize that ISG15 secreted from the site of infection is important for reducing excessive deleterious inflammation in chlamydial infection." (PMID 40627782, 2025).
cholangiocarcinoma (1 paper, 2024). A carcinoma that arises from the intrahepatic biliary tree (intrahepatic cholangiocarcinoma) or from the junction, or adjacent to the junction, of the right and left hepatic ducts (hilar cholangiocarcinoma). "We analyzed the expression levels of Type I interferons and ISG genes in the tumor tissues of patients and normal control tissues, revealing a consistent upregulation of ISG genes, including ISG15, MX1, MDA5, IFIT2, IFIT3, IRF1 and IRF7, in the tumor tissues of patients with cholangiocarcinoma." (PMID 38817870, 2024).
chronic granulomatous disease (1 paper, 2022). Chronic granulomatous disease (CGD) is a rare primary immunodeficiency, mainly affecting phagocytes, which is characterized by an increased susceptibility to severe and recurrent bacterial and fungal infections, along with the development of granulomas. "Genetic defects in PNP, PIK3CD, STAT1, ISG15, IL2RB, GS3, DNASE2 and genes associating chronic granulomatous disease were found among 7 of the 25 patients who underwent genetical testing." (PMID 35964089, 2022).
chronic hepatitis B (1 paper, 2020). "Our previous study also showed that the pre-treatment expression of ISGs (ISG15, MxA, etc) was significantly up-regulated in hepatocytes of some patients with chronic hepatitis B." (PMID 32248821, 2020).
chronic rhinosinusitis (1 paper, 2024). Chronic form of sinusitis. "There was a high proportion of IFNactive neutrophils, IFN_experienced neutrophils, Isg15_Neu, and ISG15/Ifit3_Neu in chronic rhinosinusitis." (PMID 38319415, 2024).
chronic viral hepatitis (1 paper, 2024). "Isg15 is one of the few genes shown to be elevated in the blood of patients with chronic viral hepatitis treated with IFNα." (PMID 39337564, 2024).
Crohn disease (1 paper, 2023). A gastrointestinal disorder characterized by chronic inflammation involving all layers of the intestinal wall, noncaseating granulomas affecting the intestinal wall and regional lymph nodes, and transmural fibrosis. "In active ulcerative colitis and Crohn’s disease, intestinal epithelial cells express immunomodulatory ISG15 via JAK1-STAT-IRF9." (PMID 37368693, 2023).
dilated cardiomyopathy (1 paper, 2023). Cardiomyopathy which is characterized by dilation and contractile dysfunction of the left and right ventricles. "By RNA sequencing of 64 human LV samples comprising 14 nonfailing hearts, 37 LV samples from patients with dilated cardiomyopathy (DCM), and 13 LV samples from patients with ischemic cardiomyopathy (ICM), ISG15 was found to be upregulated 1.4- to 1.7-fold in either DCM or ICM." (PMID 37115698, 2023).
ductal carcinoma in situ (1 paper, 2008). "In ductal carcinoma in situ ISG15 expression was more intense than in normal breast tissue." (PMID 18627608, 2008).
endotoxemia (1 paper, 2020). "Finally, we identified and verified 9 key genes (Cd274, Cxcl1, Cxcl9, Icam1, Ifit2, Isg15, Stat1, Tlr2, and Usp18), and we predicted seven potential drugs for multi-organ damage in LPS-induced endotoxemia." (PMID 33330617, 2020).
enterovirus infection (1 paper, 2021). "Type I-IFN plays a critical role in the innate immune response as the first line of defense against enterovirus infection and regulates many immune responsive genes, including IFN-β, IFI-27, ISG15, and OAS-1." (PMID 34485180, 2021).
Erythema (1 paper, 2021). Redness of the skin, caused by hyperemia of the capillaries in the lower layers of the skin. "To further assess the expression of ISGs in patients’ pretreated skin lesions (erythema, vesicle or erosion), we performed immunohistochemistry to detect type I IFN-inducible proteins such as MxA and ISG15." (PMID 34848794, 2021).
experimental autoimmune encephalomyelitis (1 paper, 2024). An autoimmune demyelinating disease of the central nervous system that is produced experimentally in animals by the injection of homogenized brain or spinal cord in Freund's adjuvant. "Another group reported that ISG15 gene expression and ISGylated proteins are upregulated in demyelinating neurons in experimental autoimmune encephalomyelitis and upon cuprizone-induced demyelination." (PMID 38594382, 2024).